PROM1 (prominin 1)
Diseases named in the same sentence as PROM1 in open-access papers (continued):
Sharing a sentence is not in itself a finding about the gene and the disease.
colorectal cancer (337 papers, 2008 to 2026). A primary or metastatic malignant neoplasm that affects the colon or rectum. "CD133 (or Prominin-1) is an important stem cell marker in colorectal carcinoma associated with tumorigenicity and progression of the disease." (PMID 28358339, 2017). "CREB crosstalks with KRAS to promote colon carcinogenesis and positively regulates ALCAM (CD166) and PROM1 (CD133) expression, thus promoting colorectal cancer stemness and metastasis." (PMID 38233872, 2024). "High expression of PROM1, LEMD1, CLDN2, PIGR and LCN2 were associated with CRC cell migration, promoting colorectal cancer growth and metastasis." (PMID 36816926, 2023). "The expression level of PROM1, which is proposed as a biomarker for extracellular vesicles in colorectal cancer production, was also examined and showed the stimulation of the iron export system." (PMID 38139836, 2023). "For example, the introduction of an anti-CD133 Ab has been a pivot for targeted treatment against cancer, as the cell surface marker CD133 (prominin-1) has been identified in various types of cancers, such as brain, prostate, and colorectal cancer." (PMID 35163122, 2022). "In colorectal cancer (CRC) tissues, prominin-1 (CD133) is the first molecular marker used to isolate colorectal cancer stem cells (CRCSCs)." (PMID 33917482, 2021). "CD133, also known as prominin-1, is considered to be a cancer stem cell marker in fresh, surgically resected colorectal cancer samples." (PMID 28347289, 2017). "The penta-span transmembrane glycoprotein, prominin 1 (PROM1, formerly CD133), has been used as a biomarker for the identification and isolation of cancer stem cells (CSCs) from various malignancies, including colorectal cancer." (PMID 27626310, 2016). "Colorectal cancer stem cells (CSCs) express cell surface markers such as OCT4 and CD133 (AC133 or prominin 1)." (PMID 37513937, 2023). "ISG15 is upregulated in penta-span transmembrane glycoprotein prominin 1 (PROM1, also known as CD133)-positive colorectal cancer cells compared to PROM1-negative colorectal cancer cells, suggesting the involvement of ISG15 in cancer stemness." (PMID 36319753, 2022). "Besides FLYSYN, we also conceptualized an Fc-optimized mAb targeting the pentaspan transmembrane glycoprotein CD133 (prominin-1), which showed superior induction of NK cell reactivity in AML and in colorectal cancer (CRC)." (PMID 33915811, 2021). "We further conclude that Prom1 may provide a novel therapeutic target for patients with gastrointestinal conditions such as IBD, short bowel syndrome, and colorectal cancer." (PMID 25452936, 2014).
lung cancer (301 papers, 2008 to 2025). A malignant neoplasm involving the lung. "CD133 (Prominin 1) has been used to identify CSCs in lung cancer and was linked to high levels of ABCG2 and chemoresistance." (PMID 31446534, 2020). "In our current study, we identified somatic PROM1 mutation (p.S281R) in 8/550 lung cancer patients and this novel PROM1 mutation was a T to G change, resulting in an S281R amino acid change." (PMID 24484648, 2014). "Nevertheless, a few Sox2 downstream gene targets have been reported in other cancer types, including PROM1 (encoding CD133) in human lung cancer cells and ITGA6 (encoding CD49f) in human mesenchymal stem cells." (PMID 25380620, 2014). "Clinical specimens from lung cancer patients have been found to highly express CD133 (Prominin-1), a recognized CSC protein marker in various cancers." (PMID 34063628, 2021). "CSCs that highly express CD133 (prominin-1) on cellular membrane isolated from both clinical specimens of lung cancer patients and human lung cancer cells have been documented to be mediators of drug resistance and tumor initiation properties." (PMID 34349823, 2021). "Next to the formation of spherical cancer organoids, lung cancer stem cells (LCSCs) can be identified using different markers such as cell surface glycoproteins Prominin-1 (CD133) and CD44-antigen (CD44)." (PMID 33925297, 2021). "A recent study reported the identification of a point mutation at p.S281R (serine [S] changed to arginine [R] due the mutation of thymine [T] to guanine [G]) in the prominin domain of the PROM1 protein in 8/555 lung cancer patients." (PMID 31164716, 2020). "The mutation of PROM1 is novel in lung cancer and further study will investigate the role of CD133 protein in lung cancer development and progression." (PMID 24484648, 2014). "We found that SIX1, PROM1, and TFAP2A were upregulated in HIV-associated lung cancer." (PMID 30177858, 2018). "In addition, we further verified PROM1 and CRTC2 mutations in an additional 200 pairs of lung cancer and the matched normal tissue specimens." (PMID 24484648, 2014). "The data from the current study demonstrated novel PROM1 and CRTC2 mutations, which could promote lung cancer development." (PMID 24484648, 2014). "Lung cancer stem cells (LCSCs) were originally isolated using the CD133 antigen (prominin-1), which is a common stem cell marker with an unknown biological function." (PMID 23959111, 2014). "We found PROM1 mutation in 3 pairs of lung cancers and normal tissues, including 1 SCC and 2 ADCs with mutation frequency being 1.5% and CRTC2 mutation in 5 pairs of lung cancers and normal tissues, including 3 ADCs and 2 SCCs with mutation frequency being 2.5%." (PMID 24484648, 2014). "In lung cancer, CD133 expression induced by hypoxia was correlated with the binding of OCT4 and SOX2 to the PROM1 promoter." (PMID 37588219, 2024). "CD133 (prominin-1), a 5-transmembrane glycoprotein, is an established marker for CSC fraction in lung cancer." (PMID 35053430, 2022). "Among the 25 cancer-related EV proteins, 12 proteins (annexins (A1, A2, A3, A5, A6, and A11), NPRL2, CEACAM1, MUC1, PROM1, HIST1H4A, and TNFAIP3) were related to lung cancer, according to their literature survey." (PMID 35158999, 2022). "CD133 (prominin-1) is a membrane glycoprotein that is a reliable CSLC marker for leukemia and ovarian, as well as for gastrointestinal and lung carcinoma." (PMID 28881812, 2017). "CD133 (prominin-1) is a tumor stem cell marker (e.g., in lung cancer), and not detectable in normal epidermal keratinocytes (proteinatlas.com)." (PMID 29896477, 2018). "We found that mutations of PROM1 and CRTC2 in two lung cancer patients of family cases, but absent in the two healthy members." (PMID 24484648, 2014). "The role of CD133, also known as AC133 or prominin-1, has been reported in lung cancer." (PMID 24885671, 2014).
lung cancer (continued). "The stem cell marker prominin-1 (CD133), a pentaspan membrane protein, may not be the only marker, but it remains the most widely reported marker of cancer stem cells (CSCs) of lung cancer, and has been validated by different groups." (PMID 24516569, 2014).
hepatocellular carcinoma (285 papers, 2008 to 2026). A malignant tumor that arises from hepatocytes. "CD133 (prominin-1) is found in epithelial cells and associated with many solid tumours, including those related to prostate carcinoma, thyroid carcinoma, hepatoma, renal tumours, and oral cancer." (PMID 32483269, 2020). "We next examined if the absence of Ccne1 in HSCs may affect the expression of genes encoding albumin (Alb), α-fetoprotein (Afp), and CD133 (Prom1), which are established markers for hepatocytes (Alb), de-differentiated hepatoma cells (Afp) or liver cancer stem cells (Prom1)." (PMID 37620309, 2023). "Our recent study identified CD133/Prom1 in hepatocellular carcinoma (HCC) tumors to mark proliferative tumor-propagating cells with cancer stem cell-like properties, that follow a dedifferentiation trajectory towards a more embryonic state." (PMID 38030644, 2023). "Studies using various cells, including hematopoietic stem cells, neural progenitor and epithelial cells, and hepatoma cells, have demonstrated that prominin-1/CD133 can be released with membrane vesicles through an endocytic–exocytic pathway." (PMID 31890150, 2019). "Also, TCF-LEF-binding sites are present in the PROM1 gene promoter and inhibition of CBP-β-catenin interaction downregulated CD133 expression in hepatocellular cancer, which suggest a feedback loop between CD133 and β-catenin signaling." (PMID 37922108, 2024). "CD133, also known as prominin-1, is a trans-membrane glycoprotein expressed in various malignancies, such as breast carcinomas, brain tumors, pancreatic cancer, non-small cell lung cancer, hepatocellular carcinoma, and ovarian cancer." (PMID 33112567, 2020). "Prominin-1/CD133 has been used as an unique surface stem/progenitor cell marker for varied tissues, including skin, intestine, and a range of tumors, including hepatocellular carcinoma, brain tumors, and melanoma." (PMID 27472062, 2016). "The results were further validated by RT-PCR, western blot, flow cytometry or immunofluorescent staining which revealed that prominin-1, annexin A1, annexin A3, transgelin, creatine kinase B, vimentin, and EpCAM were indeed highly expressed in the CD133-positive hepatoma cells." (PMID 23170877, 2012). "Prominin 1 (PROM1) is one of a few clinically relevant progenitor markers in human alcoholic hepatitis (AH) and hepatocellular carcinoma (HCC), and mouse liver tumor initiating stem cell-like cells (TICs)." (PMID 33173221, 2020). "The depletion of KDM6B reduced the stemness of hepatocellular cancer cells, and JIB-04, a KDM4/6 inhibitor, significantly reduced the level of expression of stem cell marker genes (CD133/PROM1, CD44, LGR5, EpCAM)." (PMID 40940894, 2025). "Transforming growth factor (TGF)-β1 has been shown to induce the demethylation of PROM1 promoter P1 by inhibiting the expression of DNA methyltransferase-1 and 3β (DNMT1 and DNMT3ß) in hepatoma cells, leading to a significant upregulation of CD133." (PMID 38532366, 2024). "In hepatocellular carcinoma, DNMT1 downregulation resulted in significant demethylation of the PROM1 promoter, resulting in its enhanced expression in a mechanism dependent on TGF-β stimulation." (PMID 37189618, 2023). "Subpopulations of Huh7 hepatoma cells that did or did not express the glycosylated CD133 antigen (prominin-1) were sorted and analyzed by mass spectrometry-based comparative proteomics." (PMID 23170877, 2012). "Therefore, this study investigated the functional consequences of enhanced expression of STIM1 and Orai1 in a tumor-initiating subpopulation of Huh-7 hepatocellular carcinoma (HCC) cells that express epithelial cell adhesion molecule (EpCAM) and Prominin 1 (CD133)." (PMID 31366337, 2019).
breast carcinoma (263 papers, 2006 to 2026). "The expression of PROM1 is also associated with various types of cancer and has been extensively studied as a stem cell marker and early biomarker for lung, gastric, and breast cancer." (PMID 37761846, 2023). "In studies of prostate cancer and breast cancer, CD133, also known as Prominin 1, serves as a key surface marker for identifying tumor cells with stem‐like properties, and CD133‐positive circulating tumor cells (CTCs) have shown stem‐like potential." (PMID 41163439, 2025). "Bock et.al found that N-cadherin and PROM1 expressions were strongly correlated, which suggested the role of PROM1 in the migration of breast cancer." (PMID 36193308, 2022). "LINC02188 has been shown to be upregulated in triple-negative breast cancers, while PROM1, ROPN1, GABRP, and FDCSP were previously associated with a cancer stem cell signature in a basal-like breast cancer phenotype." (PMID 33525353, 2021). "PROM1 is commonly reported as a marker of neuronal and hematopoietic stem cells, but it is also expressed in CSCs and cancer cells, including in breast cancer, acute myeloid leukemia (AML), and various pediatric brain tumors." (PMID 31164716, 2020). "For example, an analysis of the GEO dataset, GSE12093, showed that the probability of long-term survival of a patient with breast cancer was higher with higher levels of PROM1 expression, whereas an analysis of dataset GSE11121, gave the opposite result." (PMID 31164716, 2020). "Up-regulation of PROM1 increases the invasive capability, metastasis and drug-resistance of breast cancers." (PMID 30517191, 2018). "In this context, it will be interesting to determine if the number of prominin-1–positive cells is increasing in bloodstream as previously demonstrated in breast carcinoma and non-small cell lung cancer patients." (PMID 24911657, 2014). "An analysis of tumors with the most recurrent outlier loss, ESR1, revealed concurrent upregulation of genes typically expressed in basal breast cancers, such as PROM1, KLK7, and NDRG1, suggesting a selection of a more basal-like phenotype in endocrine-resistant disease." (PMID 33407744, 2021). "Indeed, PROM1 has been shown to mediate endocrine therapy resistance in breast cancer models through IL6/Notch3 signaling." (PMID 33407744, 2021). "In addition, PROM1 (prominin 1) was found upregulated in HIV-positive breast cancer samples, a gene commonly overexpressed in ovarian, esophageal and liver cancer." (PMID 33194615, 2020). "Except PROM1, the other genes had a diagnose value for breast cancer bone metastasis." (PMID 30918839, 2019). "CD133 (prominin-1) is a pentaspan glycoprotein over-expressed on several types of CSCs and is an independent prognostic factor for clinical outcome in patients with malignant glioma and colon and breast carcinomas." (PMID 31888091, 2019). "The association of HIF-1α and PROM1 expression in ER- breast cancers is not surprising, given that hypoxia is a potent stimulator of ERα degradation." (PMID 22225988, 2012). "Furthermore, PROM1 has been identified as a stem cell marker in esophageal and breast cancers." (PMID 31164716, 2020). "Gene expression correlation analysis revealed that USP30 negatively correlates with the expression of stem cell markers such as MMP2, MMP9, MYC, OCT4(POU5F1), NANOG, ALDH1A3, CD133 (PROM1), EPCAM, CD24, and ITGA6 in breast cancer cohorts." (PMID 41306556, 2025). "Like PROM1 and KLK7, NDRG1 is most highly expressed in basal breast cancers; yet, when expressed in ER-positive primary tumors, NDRG1 confers significantly worse disease-specific survival outcomes." (PMID 33407744, 2021).
breast carcinoma (continued). "PROM1 and LAMB3 showed lower protein levels in HIV-negative breast cancer tissues compared in those found in HIV-positive breast cancer tissues." (PMID 33194615, 2020). "To biologically validate these findings, we performed IHC assay to detect the expression of four proteins (PROM1, LAMB3, SLC6A4, and MRPS12) generated from those genes found to be differentially expressed in HIV-positive breast cancer samples." (PMID 33194615, 2020). "Moreover, TNBCs are also enriched in the expression of transcriptional programs coupled to breast cancer stem cells (e.g., CD44, ITGA6/α6 Integrin, ALDH1A1, and CD133/PROM1) and epithelial–mesenchymal transition (EMT) programs." (PMID 39335212, 2024). "However, the role PROM1 in liver and breast cancers was not clear." (PMID 31164716, 2020).
pancreatic cancer (255 papers, 2008 to 2025). "Similarly, the glycosylation state of prominin-1 associated with EVs might be a marker for pancreatic cancer diagnosis and prognosis." (PMID 39881297, 2025). "In detail, prominin-1 is expressed in the adult pancreas, i.e. in a subset of differentiated ductal epithelia and centroacinar cells, and in pancreatic cancer stem cells." (PMID 39881297, 2025). "Heavily sialilated glycoisoform of prominin 1 (CD133) was also found in pancreatic cancer patients’ EVs and correlated with worse survival rate." (PMID 36430846, 2022). "Numerous molecular markers, including Cd24, Cd44, Prom1 (Cd133), and other genes, have been applied in order to define pancreatic cancer stem cells (CSCs)." (PMID 32429174, 2020). "CD133 (also known as prominin-1) is an established cancer stem cell marker in many cancers including pancreatic cancer." (PMID 25829252, 2015). "In patients with advanced pancreatic cancer, highly glycosylated forms of prominin-1 were found to be more strongly expressed in EVs collected from malignant ascites compared to those derived from non-malignant ascites from liver cirrhosis or patients with gastric cancer." (PMID 39881297, 2025). "Moreover, CD133, or prominin-1, has also been used to identify putative CSCs in pancreatic tumors." (PMID 25811929, 2015). "The expression of CD133/PROM1, one of the CSC markers reported in pancreatic cancer, was confirmed and particularly well expressed in PDOs." (PMID 35505283, 2022). "CD133 (human prominin-1), a kind of glycoprotein with five transmembrane regions, has been identified as a valid CSC marker in gastrointestinal cancers including gastric, liver, colorectal, pancreatic cancers and other cancers like lung, brain, and prostate cancers." (PMID 36910604, 2023).